B3GNT3 (UDP-GlcNAc:betaGal beta-1,3-N-acetylglucosaminyltransferase 3)
Description:
Beta-1,3-N-acetylglucosaminyltransferase involved in the synthesis of poly-N-acetyllactosamine. Has activity for type 2 oligosaccharides. Also acts as a core1-1,3-N-acetylglucosaminyltransferase (Core1-beta3GlcNAcT) to form the 6-sulfo sialyl Lewis x on extended core1 O-glycans.
Synonyms: b3Gal-T8; Beta3Gn-T3; TMEM3; B3GN-T3; HP10328; B3GNT-3
Tractability: Antibody: its Gene Ontology location is reachable by antibodies, with high confidence; UniProt predicts a signal peptide or a membrane-spanning region.
Target class: Enzyme; Transferase
Gene: Protein-coding gene on chromosome 19 (17,794,697 to 17,814,175, forward strand). Ensembl gene ENSG00000179913.
Subcellular location: Golgi apparatus membrane
Pathways (Reactome):
Immune System: PD-L1(CD274) glycosylation and translocation to plasma membrane
Metabolism: Keratan sulfate biosynthesis
Metabolism of proteins: O-linked glycosylation of mucins
Gene Ontology:
Molecular function: N-acetyllactosaminide beta-1,3-N-acetylglucosaminyltransferase activity; protein binding; acetylglucosaminyltransferase activity; beta-1,3-galactosyl-O-glycosyl-glycoprotein beta-1,3-N-acetylglucosaminyltransferase activity; hexosyltransferase activity
Biological process: poly-N-acetyllactosamine biosynthetic process; keratan sulfate proteoglycan biosynthetic process; glycoprotein biosynthetic process
Cellular component: Golgi membrane; plasma membrane; membrane
Genetic constraint (gnomAD): Loss-of-function variants: 7 observed, 12.77 expected, observed/expected ratio (o/e) 0.55, 90% interval 0.31 to 1.03. The upper end of that interval is the gene's LOEUF score, 1.03, which puts it in group 4 of 6, group 1 being the genes least tolerant of losing a copy. Missense variants: 400 observed, 520.41 expected, observed/expected ratio (o/e) 0.77, 90% interval 0.71 to 0.83. Synonymous variants: 201 observed, 229.75 expected, observed/expected ratio (o/e) 0.87, 90% interval 0.78 to 0.98.
Homologues: Orthologues: chimpanzee B3GNT3 (99% identical), macaque B3GNT3 (90% identical), pig B3GNT3 (74% identical), dog B3GNT3 (73% identical), guinea pig B3GNT3 (69% identical), mouse B3gnt3 (68% identical), rat B3gnt3 (67% identical), zebrafish b3gnt3.4 (49% identical), zebrafish b3gnt3.2 (48% identical), zebrafish b3gnt3.3 (48% identical), tropical clawed frog b3gnt3.2 (47% identical), zebrafish b3gnt3.1 (46% identical), and 5 more. Paralogues in human: B3GNT6 (50% identical), B3GNT7 (38% identical), B3GNT4 (37% identical), B3GNT9 (37% identical), B3GNT2 (35% identical), B3GNT8 (30% identical), B3GNT5 (26% identical), B3GALT2 (24% identical), B3GALT4 (24% identical), B3GALT5 (24% identical), B3GALT1 (23% identical), B3GALT9 (22% identical), and 3 more.
Diseases named in the same sentence as B3GNT3 in open-access papers:
B3GNT3 is named in the same sentence as 28 diseases in open-access papers, as found by Europe PMC text mining. Sharing a sentence is not in itself a finding about the gene and the disease. The quoted sentences say what the papers report.
pancreatic cancer (11 papers, 2018 to 2025). "The expression of B3GNT3 is also highly associated with immune cell infiltration in gynecologic cancers, pancreatic carcinoma, and lung adenocarcinoma." (PMID 36613882, 2022). "O-Linked glycosylation via GALNT3 and B3GNT3 has been shown to regulate differentiation of pancreatic cancer stem cells." (PMID 34367349, 2021). "Directly targeting glycosyltransferases such as B3GNT3 in pancreatic cancer or ALG3 to induce immunogenic ferroptosis represents a promising strategy, particularly given the ability of ALG3 inhibition to enhance immunotherapy responses." (PMID 41008983, 2025). "In a study on pancreatic cancer, B3GNT3 was highly expressed in cell lines, but knocking down B3GNT3 expression increased the invasiveness and metastatic capabilities of the cells." (PMID 38818465, 2024). "For example, elevated B3GNT3 expression levels in pancreatic cancer stem cells (PCSCs) regulate stemness by modulating PCSC markers and promoting tumor progression." (PMID 33316775, 2020). "B3GNT3 has been demonstrated to be an oncogene in several cancers (e.g. lung cancer, pancreatic cancer, and breast cancer), and participates in lymphocyte trafficking and migration." (PMID 33316775, 2020). "Besides, in early cervical cancer, pancreatic cancer, and neuroblastoma, the level of B3GNT3 mRNA is higher than that of adjacent control tissues." (PMID 34868228, 2021). "However, little is known about the potential functions of B3GNT3 in immunosuppression in pancreatic cancer (PC)." (PMID 33316775, 2020). "We first confirmed that high expression of B3GNT3 was positively correlated with resistance to ferroptosis inducers including RSL3, ML162, and ML210, particularly in pancreatic cancer cell lines treated with RSL3." (PMID 37479744, 2023). "Since KLF5 and TCF7L2 have been shown to be upregulated in pancreatic cancer stem cells, it would be interesting to validate if GALNT3 and B3GNT3 are driven by any of these TFs." (PMID 34367349, 2021). "Altogether, we have systematically analysed the role of B3GNT3, MGAT3, FUT3 and GCNT3 in pancreatic cancer and illustrated the mechanism of GCNT3 in PC." (PMID 32203219, 2020). "After the multi-step validation, we identified B3GNT3, B4GALNT3, FUT3, FUT6, GCNT3 and MGAT3 as top-upregulated genes in aggressive pancreatic cancer cell lines Capan-1 and HPAF/CD18." (PMID 32203219, 2020). "Among these, we successfully identified the functions of B3GNT3, GCNT3, FUT3 and MGAT3 in pancreatic cancer cells." (PMID 32203219, 2020). "Three genes (ABCA12, B3GNT3, and BMF) and eight miRNA (hsa.miR.577, hsa.miR.503, hsa.miR.3613, hsa.miR.19a, hsa.miR.19b.2, hsa.miR.365a, hsa.miR.365b, and hsa.miR.4668) were found to be dysregulated in four different stages of pancreatic cancer." (PMID 37794108, 2023). "Previous studies demonstrated that B3GNT3 participates in the development and progression of human malignancies, such as pancreatic cancer, breast cancer, cervical cancer, lung cancer, and non-Hodgkin lymphoma." (PMID 33316775, 2020).
lung adenocarcinoma (6 papers, 2022 to 2025). A carcinoma that arises from the lung and is characterized by the presence of malignant glandular epithelial cells. "Finally, B3GNT3 is associated with immune cell infiltration in lung adenocarcinoma and, with pelvic lymph node metastasis in cervical cancer patients." (PMID 40096084, 2025). "B3GNT3 is associated with poor prognosis in NSCLC, particularly in lung adenocarcinoma, where it influences cell apoptosis and holds promise as an early cancer screening marker." (PMID 40124684, 2025). "One study reported increased B3gnt3 expression levels corresponding to increased immune cell infiltration and correlated with poorer outcomes in patients with lung adenocarcinoma." (PMID 38436597, 2024). "We also confirmed that the expression of B3GNT3 protein in lung adenocarcinoma was significantly higher than in the adjacent normal tissues, consistent with the previous results." (PMID 36575396, 2022). "High expression of B3GNT3 facilitates tumorigenesis and progression and is commonly associated with unfavorable survival in PDAC and lung adenocarcinoma, but not in neuroblastoma." (PMID 37479744, 2023).
cervical cancer (5 papers, 2015 to 2025). A primary or metastatic malignant neoplasm involving the cervix. "The expression level of B3GNT3 in patients with NSCLC or early-stage cervical cancer was associated with unfavourable clinicopathological parameters." (PMID 33403045, 2021). "Our study demonstrated that elevated B3GNT3 expression is associated with pelvic lymph node metastasis and poor outcome in early-stage cervical cancer patients." (PMID 26709519, 2015). "Therefore, we assessed whether B3GNT3 is upregulated in cervical cancer and is clinically associated with the development and progression of cervical cancer." (PMID 26709519, 2015). "Previous studies have shown that B3GNT3 is highly expressed in a variety of malignant tumors such as nonsmall cell lung cancer, cervical cancer, endometrial cancer, and breast cancer." (PMID 36995820, 2023). "Here, we aimed to explore the expression pattern of B3GNT3 in cervical cancer cell lines and early-stage cervical cancer specimens." (PMID 26709519, 2015). "Intense expression of B3GNT3 protein was noted in 24.7% (21/85), 41.4% (12/29), 58.9% (33/56), and 52.2% (12/23) of cervical cancer of FIGO stage Ib1, Ib2, IIa1and IIa2, respectively (P < 0.05, χ2 test)." (PMID 26709519, 2015). "In our study cohort, the prognostic impact of B3GNT3 protein expression in cervical cancer was explored using Kaplan–Meier analysis and the log-rank test." (PMID 26709519, 2015). "B3GNT3 mRNA expression was at least 3.5-fold greater in the cervical cancer cell lines compared with NC." (PMID 26709519, 2015). "In our study, we reported that the B3GNT3 mRNA and protein were overexpressed in cervical cancer cell lines and cervical cancer samples (stages Ib-IIa)." (PMID 26709519, 2015). "IHC staining of B3GNT3 protein expression levels was analyzed further to determine their relationship with the clinicopathological characteristics of cervical cancer." (PMID 26709519, 2015). "The expression of B3GNT3 mRNA was dramatically higher in the 10 cervical cancer tissue specimens than in the paired normal tissues, with the differential expression level ranging from 4.2- to 17.4-fold." (PMID 26709519, 2015). "Nevertheless, further study extended to a larger cohort of patients with LNM, and further investigation of the mechanism by which B3GNT3 is involved in the LNM of cervical cancer, are required." (PMID 26709519, 2015). "In conclusion, this study is the first study evaluating the expression of B3GNT3 mRNA and protein in cervical cancer cell lines as well as early-stage cervical cancer specimens." (PMID 26709519, 2015). "Multivariate analysis suggested that B3GNT3 expression is an independent prognostic indicator for cervical cancer patients." (PMID 26709519, 2015). "B3GNT3 expression was significantly upregulated in cervical cancer cell lines and lesions compared with normal cells and adjacent noncancerous cervical tissues." (PMID 26709519, 2015). "Our results suggested the important role of B3GNT3 protein in the prognosis of patients with early-stage cervical cancer." (PMID 26709519, 2015). "Realtime-PCR and Western blotting analysis showed that mRNA and protein expression of B3GNT3 is upregulated in cervical cancer." (PMID 26709519, 2015). "Correlation between B3GNT3 expression and the clinicopathological features of early-stage cervical carcinoma." (PMID 26709519, 2015). "Immunohistochemistry (IHC) was performed to investigate the expression pattern of B3GNT3 protein in a retrospective cohort of 193 cervical cancer cases, including 85 cases of stage IB1 (44.1%), 29 cases of stage IB2 (15.0%), 56 cases of stage IIA1 (29.0%) and 23 cases of stage IIA2 (11.9%)." (PMID 26709519, 2015). "B3GNT3 protein levels could be used as an important prognostic marker of clinical outcome in early-stage cervical cancer patients." (PMID 26709519, 2015). "Multivariate analysis revealed that B3GNT3 expression might be an independent prognostic indicator of survival in cervical cancer patients." (PMID 26709519, 2015).
cervical cancer (continued). "B3GNT3 may be a novel prognostic marker and therapeutic target for the treatment of cervical cancer." (PMID 26709519, 2015). "However, positive staining for B3GNT3 protein was seen in cervical cancer specimens." (PMID 26709519, 2015). "Thus, our results indicated that B3GNT3 protein may represent a potential prognostic indicator for early-stage cervical cancer patients." (PMID 26709519, 2015). "In the present study, we showed, for the first time, that expression of B3GNT3 protein is upregulated in cervical cancer and correlates with clinical characteristics, especially PLNM of patients with early-stage cervical cancer." (PMID 26709519, 2015). "Western blotting analysis showed that all eight cervical cancer cell lines (MS751, C33A, Hela, HeLa229, SiHa, HCC94, CaSki, and ME-180) exhibited significantly higher levels of B3GNT3 protein compared with NC." (PMID 26709519, 2015). "Higher levels of B3GNT3 protein expression were observed in HPV-positive cervical cancer tissues (44.4%), whereas HPV-negative cases expressed less B3GNT3 (25%)." (PMID 26709519, 2015). "The present study demonstrated that B3GNT3 is an oncogene in early-stage cervical cancer and further exploration of the mechanism by which B3GNT3 is involved in the progression and LNM of cervical cancer is required." (PMID 26709519, 2015). "Finally, we found a significant association between shorter OS and high B3GNT3 protein expression in the “without lymph node metastasis” subgroup, which suggested that B3GNT3 might be a useful marker to predict poor overall survival of cervical cancer patients without LNM." (PMID 26709519, 2015).
lung carcinoma (5 papers, 2020 to 2022). "As with LAD1, poor clinical outcomes were significantly associated with increased B3GNT3 expression in lung cancer patients." (PMID 36613882, 2022). "B3GNT3 is an important member of B3GlcNacT family, and it was found important in the development of lung cancer." (PMID 35211471, 2022). "In lung cancer cells, miR-149-5p has been found to down-regulate the expression of B3GNT3, an oncogene that influences lung cancer cell proliferation and invasiveness." (PMID 35008841, 2021). "Besides, β1, 3-N-acetylglucosaminyltransferase-3(B3GNT3) was reported be abnormally expressed in lung cancer, and the overexpression of B3GNT3 is related to the poor prognosis of patients with lung cancer." (PMID 34722295, 2021). "Taken together, the results of our study provided evidence that the upregulation of LAD1 and B3GNT3 in LUAD and is a possible mechanism related to the increased mesenchymal phenotype in lung cancer and to the remodeling of the tumor microenvironment." (PMID 36613882, 2022). "Further studies indicated miR-149-5p had a negative regulatory effect on lung cancer progression, and downregulating the expression of B3GNT3 by directly targeting 3’-UTR of B3GNT3." (PMID 34722295, 2021). "B3GNT3 protein expression was significantly correlated with tumor grading in lung cancer cells but not FUT3 (the only two available data from CPTAC)." (PMID 36613882, 2022).
neuroblastoma (5 papers, 2015 to 2024). Neuroblastoma (NB) is the most common solid, extracranial childhood tumor. "Recently, Ho reported that B3GNT3 might play an important role in suppressing the malignant phenotypes of neuroblastoma cells, including migration and invasion, by suppression of FAK, Akt and ERK, which are important downstream signaling molecules for integrins and numerous growth factor receptors." (PMID 26709519, 2015). "However, Ho reported that B3GNT3 might play a critical role in suppressing the malignant properties of neuroblastomas and its altered expression might contribute to the pathogenesis of neuroblastoma." (PMID 26709519, 2015).
breast carcinoma (4 papers, 2020 to 2026). "Beta-1,3-N-acetylglucosaminyltransferase 3 (B3GNT3) has been associated with tumor progression in several solid tumors, and inhibits CD8+ T cell-mediated anti-tumor immunity in breast cancer." (PMID 33316775, 2020). "Glycosylation-related enzymes such as calcium-activated nucleotidase 1 (CANT1) and Beta-1,3-N-acetylglucosaminyltransferase 3 (B3GNT3) have been implicated in tumour progression, yet their roles in breast cancer, particularly invasive ductal carcinoma (IDC), are not well defined." (PMID 41540462, 2026).
lymph node metastasis (3 papers, 2015 to 2026). "A potential biomarker, B3GNT3, was identified as a key gene that was negatively associated with lymph node metastasis and positively correlated with prognosis." (PMID 38818465, 2024). "Similarly, in our cohort, low expression of B3GNT3 was associated with several risk factors, including advanced pTNM stage and a higher probability of lymph node metastasis, which contribute to poor prognosis." (PMID 38818465, 2024). "B3GNT3 expression was lower in patients with positive lymph node metastasis, implying a potential involvement of B3GNT3 in lymph node metastasis." (PMID 38818465, 2024). "High B3GNT3 protein expression tend to be strongly correlated with HPV infection, FIGO stage, tumor size, tumor recurrence, vital status, concurrent chemotherapy and radiotherapy, lymphovascular space involvement and most importantly, lymph node metastasis." (PMID 26709519, 2015). "In addition, we observed a correlation between OS and high B3GNT3 protein expression in the “without lymph node metastasis” and “with lymph node metastasis” subgroups." (PMID 26709519, 2015). "Moreover, IHC and statistical analysis indicated that overexpression of B3GNT3 protein is correlated with HPV infection, FIGO stage, tumor size, tumor recurrence, vital status, concurrent chemotherapy and radiotherapy, lymphovascular space involvement and especially, lymph node metastasis." (PMID 26709519, 2015).
colon cancer (2 papers, 2015 to 2020). "B3GNT3 is likely to be the most probable candidate involved in the biosynthesis of the backbone structure of dimeric sialyl Lewis A (Galβ1–3GlcNAcβ1–3Galβ1–3GlcNAc), which is a cancer associated glycosphingolipid antigen in human colon cancer tissues and the colon cancer cell line Colo205." (PMID 26709519, 2015). "Shiraishi demonstrated that B3GNT3 was highly expressed in the colon cancer cell line Colo205." (PMID 26709519, 2015). "However, it is reported that B3GNT3 protein participates in the development and progression of human cancers, such as non-Hodgkin lymphoma (NHL), colon cancer, esophageal squamous cell cancer (OSCC), and pancreatic and hepatocellular cancers." (PMID 26709519, 2015).
non-Hodgkin lymphoma (2 papers, 2015 to 2018). Distinct from Hodgkin lymphoma both morphologically and biologically, non-Hodgkin lymphoma (NHL) is characterized by the absence of Reed-Sternberg cells, can occur at any age, and usually presents as a localized or generalized lymphadenopathy associated with fever and weight loss. "Expression of B3GNT3 is also involved in the development and progression of many cancers, including non-hodgkin lymphoma (NHL), colon, pancreatic, esophageal squamous cell, hepatocellular, and cervical." (PMID 30466404, 2018).
esophageal squamous cell carcinoma (1 paper, 2023). Esophageal squamous cell carcinoma (ESCC) is a type of esophageal carcinoma (EC) that can affect any part of the esophagus, but is usually located in the upper or middle third. "B3GNT3 function was measured using KYSE-30 and KYSE-410 cells of esophageal squamous cell carcinoma (ESCC) cell lines." (PMID 36995820, 2023).
ovarian tumor (1 paper, 2023). "We observed 24 ABH antigen synthesis‐related genes in which five genes (FUT1, FUT2, FUT3, B3GNT3, and B3GNT2) were up‐regulated and three genes (ST3GAL3, ST3GAL4, and B3GALT2) were down‐regulated in ovarian tumor tissue versus adjacent tissues in all samples." (PMID 36415180, 2023).
schizophrenia (1 paper, 2017). A major psychotic disorder characterized by abnormalities in the perception or expression of reality. "Recently, protein levels of important glycosylation enzymes, B3GNT8 and MGAT4A, were found decreased in the prefrontal cortex in schizophrenia (12 case–control pairs), whereas in our study B3GNT1, B3GNT3 and MGAT1 transcripts were downregulated in schizophrenia cases." (PMID 28418402, 2017).
stomach cancer (1 paper, 2021). "Also consistent with the decrease in bi-GlcNAc core-2 structures in gastric cancer, low expression of B3GNT3 in stomach cancer is significantly associated with decreased overall survival." (PMID 34404781, 2021).
systemic lupus erythematosus (1 paper, 2023). An autoimmune multi-organ disease typically associated with vasculopathy and autoantibody production. "B3GNT3 may be involved in viral carcinogenesis, neutrophil extracellular traps and systemic lupus erythematosus signaling pathways of ESCA by transcriptome sequencing." (PMID 36995820, 2023).